APOE (apolipoprotein E)
Diseases named in the same sentence as APOE in open-access papers (continued):
Sharing a sentence is not in itself a finding about the gene and the disease.
Onset (continued). "Genetic factors also modulate disease risk: the apolipoprotein E (ApoE) ε4 allele is the strongest known genetic susceptibility factor for late-onset AD, whereas mutations in amyloid precursor protein (APP), presenilin-1 (PSEN1), and presenilin-2 (PSEN2) cause rare familial forms of early-onset AD." (PMID 41373799, 2025). "To date, APOE is still the strongest genetic risk factor for late-onset AD, although the precise mechanisms governing the APOE expression remain unclear." (PMID 38674351, 2024). "Although multiple factors and cellular pathways may precipitate AD, individuals with the ε4 allele of the apolipoprotein E (APOE-ε4) gene have an increased risk of late-onset AD." (PMID 37238686, 2023). "However, three early-onset familial AD genes (APP, PSEN1, and PSEN2) and one genetic risk factor for late-onset AD (APOE) have been identified." (PMID 31080696, 2019). "Our results supported that APOE-e4 is the major genetic risk for late-onset AD." (PMID 30852398, 2019). "This experiment showed that Zn water caused significant impairments in a mouse model of late-onset AD, containing the ApoE ε4 allele; consequently, studies on the role of metals in AD need to take into account the ApoE status of either the human subjects or the mouse models." (PMID 25374537, 2014). "Genetic variations in VPS13 genes are emerging risk factors for sporadic, late-onset AD, with VPS13 variants exceeding even ApoE in risk contribution." (PMID 40931359, 2025). "Carriers of the Apolipoprotein E (APOE) ε4 allele, i.e. the strongest genetic risk factor for sporadic late-onset AD, appear at higher risk of AD-related psychosis, although this finding has not been replicated by all studies." (PMID 35727357, 2023). "Through genome-wide association studies and other methods, it has been found that many genes related to lipid metabolism, immune response, and endocytosis are correlated with the occurrence of late-onset AD, including APOE, TREM2, PICALM, and CLU." (PMID 33806413, 2021). "Apolipoprotein E (APOE) ε4 allele is the major risk factor for sporadic, late-onset AD (LOAD), which comprises over 95% of AD cases, increasing the risk of AD 4-12 fold." (PMID 33846280, 2021). "The Apolipoprotein E gene (APOE) is critically associated with AD, with APOE4 representing the strongest genetic risk factor for the development of late-onset AD." (PMID 24971061, 2014). "However, the presence of an APOE e4 allele is a significant risk factor for PCA, a type of atypical early-onset AD; although the risk conferred by the gene for PCA is reduced compared with typical AD." (PMID 29220823, 2018). "Peripheral CHI3L1 expression was elevated in individuals with early-onset AD (EOAD), particularly among APOE ε4 carriers (EOAD APOE ε4+, n = 13 vs. EOAD APOE ε4-, n = 8; p = 0.026)." (PMID 41425914, 2025). "We identified a selective increase in CHI3L1 transcript levels in early-onset AD (EOAD), particularly among APOE ε4 carriers." (PMID 41425914, 2025).
aortic aneurysm (74 papers, 2012 to 2025). A ruptured aneurysm located in the wall of the proximal portion of the descending aorta proceeding from the arch of the aorta. "For example, salvianolic acid A (Sal-A) attenuates aortic aneurysm formation in apolipoprotein E(ApoE)-deficient mice." (PMID 36748219, 2023). "Acute aortic aneurysms and lethal ruptures were induced by angiotensin II (Ang II) administration to apolipoprotein E (ApoE)-deficient mice fed throughout the entire experiment with a Western diet (WD)." (PMID 37630330, 2023). "Using models of aortic aneurysm in AngII-infused ApoE deficient mice, and in Marfan-like mice we found inhibition of aortic wall degeneration by peri-aortic LepA application in the ascending aorta." (PMID 35015765, 2022). "Metformin can remove glycocalyx barrier in db/db mice, and relieve Ang-II-caused atheromatous plaque generation and aortic aneurysm in ApoE (−/−) mice." (PMID 33117278, 2020). "We examined the effect of FXa/FIIa inhibition on experimental aortic aneurysm in apolipoprotein E-deficient (ApoE−/−) mice infused with angiotensin II (AngII)." (PMID 28220880, 2017). "Ang II infusion in atherosclerotic Apolipoprotein E (Apo-E) deficient mice has been employed as a model of aortic aneurysms." (PMID 26925344, 2016). "ApoE−/− mice were significantly more susceptible to aortic aneurysm rupture in comparison with Rgs1−/−ApoE−/− mice, with 56% survival in ApoE−/− mice versus 94% in the Rgs1−/−ApoE−/−group." (PMID 25782711, 2015). "Murine MSC deficient in apolipoprotein E (ApoE) incorporate into the aorta and reduce angiotensin II-induced aortic aneurysm formation in ApoE-deficient mice." (PMID 25144321, 2014). "The inflammatory response is also evident in animal models, such as apolipoprotein E-deficient (ApoE-/-) mice that have been infused with angiotensin II, prior to development of aortic aneurysm." (PMID 25398022, 2014). "Consequently, high-dose statins suppressed aortic aneurysm development by reducing the endoplasmic reticulum stress signaling pathway in apolipoprotein E-deficient (ApoE–/–) mices used as animal models of abdominal aortic aneurysm." (PMID 35571155, 2022). "Significant increases in chymase and MMP-9 activities were also observed in a mouse aortic aneurysm model that was developed by continuous administration of angiotensin II to apolipoprotein E-deficient mice, and expansion of the aortic aneurysm was also prevented by chymase inhibitors." (PMID 36289761, 2022). "Furthermore, CYP1B1 has been shown to contribute to the development of atherosclerosis, hypertension, and angiotensin II-induced aortic aneurysm in male apolipoprotein E-deficient mice." (PMID 33185690, 2020). "Similarly, prior work using the apolipoprotein E deficient mouse model of aortic aneurysms found an activation of the same pathway in the aortas of animals treated with angiotensin II as compared with controls." (PMID 25993291, 2015). "We previously reported that intra-abdominal implantation of bone marrow-derived MSCs (BM-MSCs) sheet by laparotomy attenuated angiotensin II (AngII)-induced aortic aneurysm (AA) growth in apolipoprotein E-deficient (apoE−/−) mice through anti-inflammation effects." (PMID 23875706, 2013). "Another study showed that metformin attenuated angiotensin II induced aortic aneurysm in ApoE(-/-) mice by reducing monocyte infiltration." (PMID 37280690, 2023). "Intraperitoneal injection of glycolysis inhibitors and 2-deoxyglucose significantly attenuated aortic aneurysm formation in male C57BL/6J mice with CaCl2-induced abdominal aorta dilatation or male ApoE KO mice with decreased angiotensin II infusion." (PMID 35637715, 2022). "Antagomir-29b significantly reduces aortic aneurysm diameter in ApoE−/− mice, whereas the miR-195 serum level corresponds with the aortic aneurysm diameter in humans." (PMID 36430208, 2022).
aortic aneurysm (continued). "In ApoE−/− mice, its suppression by anti-miR-181b reduced the formation of aortic aneurysms, increased the fibrotic response, and stabilized atherosclerotic plaques or aneurysms." (PMID 36430208, 2022). "Atheroma formation in ApoE-deficient mice and LDL receptor-deficient mice and aortic aneurysm formation in osteoprotegerin-deficient/ApoE-deficient mice were prevented by orally administered EPA through anti-inflammatory effects." (PMID 32751754, 2020). "We investigated the role of tropoelastin as a new imaging marker of dysfunctional matrix turnover in aortic aneurysms and dissections in the Ang II-infused ApoE-/- murine model and excised human aortic aneurysmal tissue." (PMID 31282949, 2020). "Most notably, chronic infusion of angiotensin II (AngII) in male apolipoprotein-E null (ApoE−/−) mice yields a reproducible model of dissecting aortic aneurysm, which often includes a false lumen with intramural thrombosis." (PMID 29410467, 2018). "AngII infusion induces aortic aneurysm formation in ApoE−/− mice with the suprarenal aorta (SRA) being the common aortic site affected." (PMID 28220880, 2017). "We examined the effect of the anticoagulants enoxaparin, fondaparinux, and dabigatran on growth of experimental aortic aneurysm in the AngII-infused ApoE−/− mouse model." (PMID 28220880, 2017). "Overexpression of TIMP-1 expression results in reduction in plaque area in apoE−/− mice and ease of aortic aneurysm degeneration and rupture in rat model 41,42." (PMID 25661015, 2015). "We observed that recipient mice transplanted with ApoE−/− bone marrow were more prone to aortic aneurysm rupture in comparison with mice receiving Rgs1−/−ApoE−/− bone marrow." (PMID 25782711, 2015). "Metformin was found to improve glycocalyx barrier properties in db/db mice, attenuate Ang-II-induced atheromatous plaque formation and aortic aneurysm in ApoE(−/−) mice." (PMID 26453464, 2015). "Furthermore, a recent study demonstrated in apolipoprotein E-deficient mice that it is possible to limit the inflammatory process by blocking TLR4/c-Jun N terminal kinase signaling pathway with Rosiglitazone in the initiation stages of aortic aneurysm development." (PMID 25120286, 2014). "We previously reported that intra-abdominal implantation of BM-MSCs sheets by laparotomy inhibited the development of Ang II-induced aortic aneurysm in apoE−/− mice by anti-inflammation and elastin preservation." (PMID 23875706, 2013). "We found that the incidence of aortic aneurysm formation as well as elastic fiber degradation was significantly decreased in EP4+/−/ApoE−/− mice." (PMID 22570740, 2012). "Aortic aneurysms developed in 67% of Ang II-infused ApoE−/− mice fed with standard chow and water alone (n = 15), and 40% died of rupture." (PMID 23226500, 2012). "Subsequently, to investigate whether macrophage Tsc2 is crucial to maintain vasculature homeostasis, we crossed myeloid-specifc Tsc2MKO with hyperlipidemic ApoE–/– mice and established AngII-induced murine aortic aneurysm model." (PMID 36400753, 2022). "ApoE-/- mice stimulated with angiotensin II develop aortic aneurysms and atherosclerotic plaques, but when these mice also overexpressed human sclerostin or were injected with recombinant mouse sclerostin they were protected from aortic aneurysms and atherosclerosis." (PMID 33776907, 2021). "In conclusion, adventitial thickening with collagen accumulation induced by AngII infusion may increase the strength of aortic tissue and potentially limit the development of aortic aneurysms and dissection in ApoE-/-Opg-/- mice." (PMID 32614927, 2020). "Furthermore, miR-144-5p was found to regulate TLR2 signaling and the progression of aortic aneurysms following Ang II administration in apolipoprotein E knockout mice." (PMID 33318302, 2020). "All imaging was performed with an ApoE knockout mouse-model for aortic aneurysms." (PMID 28582441, 2017).
aortic aneurysm (continued). "Moreover, we illustrated that metformin, which had proven to be an AMPK activator, significantly attenuated Ang II-induced aortic aneurysm in ApoE−/− mice." (PMID 29190959, 2017). "Aortic aneurysms from Ang-II-infused ApoE−/− mice exhibited a similar HDAC expression profile." (PMID 26989193, 2016). "For this, the authors utilized 9–10 weeks old apolipoprotein E-deficient (ApoE-/-) mice that were treated with angiotensin II (AngII, 1000 ng/kg/min) via aortic minipumps and in parallel fed with a HFD (2% cholesterol and 20% fat) for 28 days to foster the development of aortic aneurysms." (PMID 38396989, 2024). "To further evaluate the roles of FAM3A in the development of aortic aneurysms, we constructed murine AAA models using angiotensin II (AngII)-infused ApoE−/− mice and elastase-treated C57BL/6 mice." (PMID 37660071, 2023). "For example, use of male mice, high fat diet (western diet) or genetic modifications such as low-density-lipoprotein (LDL) receptor or apolipoprotein E knockout increase the incidence of aortic aneurysms, without providing explicit insight into the dissection process." (PMID 34572082, 2021). "Whilst performing BMT into irradiated ApoE−/− mice, to generate bone marrow chimeric animals to assess leukocyte gene function in AAA, we observed that BMT mice infused with Ang II at 0.8 mg/kg/day did not develop aortic aneurysms in comparison with non-irradiated mice receiving this dose." (PMID 30048944, 2018).
breast carcinoma (74 papers, 2004 to 2025). "Another larger meta-analysis found a contradictory significant association between the APOE ε4 allele and increased breast cancer risk in Asian populations." (PMID 40149482, 2025). "Like PCa, ApoE has been suggested as a promising diagnostic and prognostic biomarker for breast cancer." (PMID 40149482, 2025). "Liu and colleagues also observed that the APOE ε2 allele had a protective effect, reducing the risk of breast cancer." (PMID 40149482, 2025). "A meta-analysis by Saadat (2012) suggested that the APOE ε4 allele posed a relatively low risk for breast cancer susceptibility, particularly in Asian populations." (PMID 40149482, 2025). "Single-cell analysis in breast cancer has revealed that SPP1-positive tumor-associated macrophages (TAMs) display significantly increased expression of markers like apolipoprotein E (APOE), CD204, CD68, and CADM1." (PMID 39727934, 2024). "We also previously demonstrated a potentially altered relationship between APOE genotype and neurogenesis in patients with breast cancer and there is some evidence suggesting an association between APOE e4 genotype and breast cancer pathogenesis." (PMID 37127832, 2023). "Our group and others have shown that the APOE e4 genotypic variant is associated with lower cognitive function in breast cancer." (PMID 37127832, 2023). "Genetic polymorphisms of APOE have been reported to influence the growth and progression of many cancers, including colon cancer, breast carcinoma, and primary brain tumor." (PMID 36675580, 2023). "ApoE is associated with metastasis and tumor growth, progression and staging in various types of cancer and increased ApoE levels directly proportional to the plasma HDL levels indicating an increased risk of breast cancer." (PMID 35645371, 2022). "The expression of APOE also correlates with certain gender-associated tumors including, ovarian cancer, uterine carcinosarcoma, and breast cancer." (PMID 37304007, 2022). "By contrast, in a clinical study, it has been shown that the apoE plasma concentration is positively associated with breast cancer malignancy." (PMID 35268435, 2022). "This prospective longitudinal study of breast cancer survivors (n = 167) examined the association of apolipoprotein ε4 (APOE ε4) genotype with cognition and interactions with chemotherapy or endocrine therapy up to 6 years after treatment." (PMID 34480030, 2021). "More recent prospective study by the same authors examined the association between post-treatment cognitive changes, APOE status and smoking history in breast cancer patients treated with adjuvant therapy." (PMID 34970595, 2021). "For 26 APOE-cancer association studies, breast cancer was reported in 10 studies, colorectal cancer in 8 studies, multiple cancers in 3 studies, prostate cancer in 2 studies, gastric, head and neck, hepatocellular cancers respectively in 1 study." (PMID 25820350, 2015). "Recent studies of relative risk based on large samples argue that the impact of APOE e4 on AD risk is similar to that of major genes in Mendelian diseases and comparable to genetic risk of breast cancer." (PMID 22693679, 2012). "These suggest that genetic and ethnic factors (perhaps including diet) may influence the relationship between APOE variants and breast cancer risk and incidence." (PMID 40149482, 2025). "In breast cancer, ApoE may be more intricately linked to cancer development since inheritance of APOE ε2, ε3, and ε4, each appear to exert distinct effects on susceptibility and progression." (PMID 40149482, 2025). "APOE ε4 female patients display elevated TG levels and an increased risk of breast cancer." (PMID 39763652, 2024). "APOE alleles are involved in the development and progression of various malignancies, such as hepatocellular carcinoma, testicular cancer, pancreatic cancer, melanoma, colorectal cancer and breast cancers." (PMID 39763652, 2024).